CCND1 (cyclin D1)
Diseases named in the same sentence as CCND1 in open-access papers (continued):
Sharing a sentence is not in itself a finding about the gene and the disease.
mesothelioma (10 papers, 2012 to 2025). A usually malignant and aggressive neoplasm of the mesothelium which is often associated with exposure to asbestos. "Human mesotheliomas overexpressing Merlin reduce its proliferation rate by down-regulating cyclin D1 expression through PAK signaling pathway." (PMID 29715273, 2018). "YAP enhances the proliferation of malignant mesothelioma cells by directly upregulating cyclin D1 (CCND1)." (PMID 30463366, 2018). "Mesothelioma cell lines were useful tools to demonstrate that the NF2 tumour suppressor gene product, merlin, exerts its anti-proliferative effect in mesothelioma by suppression of p21 activated kinase-induced cyclin D1 expression." (PMID 23516439, 2013). "Cafestol and kahweol modulated the promoter activity and protein expression level of the Sp1 regulatory genes including Cyclin D1, Mcl-1, and Survivin in mesothelioma cells." (PMID 22734486, 2012). "STAT3 activity was markedly decreased in mesothelioma specimens from SC144-treated mice, and in vitro treatment of mesothelioma cells with SC144 markedly reduced the expression of the STAT3 downstream effectors, cyclin D1 and survivin." (PMID 38784478, 2024). "Cyclin D1 and CDK4/6 (cyclin-dependent kinases 4 and 6) proteins are responsible for progression through G1 to S phases, a step which is often deranged in many cancers, including mesothelioma." (PMID 36232554, 2022). "Given that YAP promotes TEA domain family member 1 (TEAD)-mediated transcription of cell cycle genes, such as CCND1 and FOXM1, one study found that silencing YAP in mesothelioma resulted in suppression of these genes and inhibition of cell motility, invasion and anchorage-independent growth." (PMID 29342862, 2018).
metastasis (10 papers, 2006 to 2025). The spread or migration of cancer cells from one part of the body (where they first appeared) to another. "In EC tumor tissues, elevated protein levels of cyclin D1, Beclin1, ATG5, ATG7, and LC3 are observed, and upregulation of cyclin D1 is significantly associated with lymph node metastasis in EC." (PMID 41209546, 2025). "Our results indicate that EGFR and CCND1 CNAs are significantly associated with clinical stage, tumor differentiation, and lymph node metastasis." (PMID 31159251, 2019). "In ESCC, CCND1 amplification or overexpression is also significantly correlated with lymph node metastasis." (PMID 31289612, 2019). "Expression of ANO1 was significantly associated with distant metastatic relapse (P < 0.001), latent bone metastasis (P = 0.011), and β-catenin expression (P = 0.002), cyclin D1 expression (P = 0.004), MMP expression (P = 0.023), and snail expression (P = 0.001)." (PMID 29416639, 2018).
oropharyngeal carcinoma (10 papers, 2013 to 2026). Carcinoma, predominantly squamous cell, arising from the epithelial cells of the oropharynx. "The association between cyclin D1 and overall mortality also remained significant in papers examining only oropharynx cancer (HR = 2.66, P = .03)." (PMID 41988332, 2026). "Since cyclin D1 overexpression has been associated with a poor prognosis in cancers of other head and neck regions, we hypothesize it is associated with a poor prognosis in oropharyngeal cancer." (PMID 23672832, 2013). "Our data for HPV- oropharyngeal cancer indicate that the frequency of CCND1 amplification (in approximately 55% of cases) and CDKN2A/B deletions (in approximately 55% of cases) are higher than previously reported." (PMID 23718828, 2013).
parathyroid carcinoma (10 papers, 2008 to 2025). "Previous reports have suggested that a history of neck irradiation, long‐standing secondary HPT, end‐stage renal disease, hereditary HPT‐jaw tumor syndrome, and mutations of parafibromin (HRPT2) and cyclin D1 (CCND1) increase the risk of parathyroid carcinomas." (PMID 36188029, 2022). "Recently, it has been raised the possibility that treatment with drugs used in other tumors, directed to mutations of PIK3CA or MTOR or amplification of CCND1, can also be used in metastasized parathyroid carcinoma, as these mutations are also frequent in this neoplasia." (PMID 32884778, 2020). "Several scientific teams have evaluated immunohistochemical expression of cyclin D1 in parathyroid carcinoma." (PMID 35805976, 2022).
prostate adenocarcinoma (10 papers, 2007 to 2025). "Our study results revealed lower immunoreactivity and expression of genes encoding β-catenin, Fzd8, Wnt5a, and cyclin D1 and significantly higher fluorescence intensity of miRNA 106a-5p and 375-3p with prostate adenocarcinoma compared to BPH." (PMID 41465498, 2025). "In prostatic adenocarcinoma, cytoplasmic-membranous Ccnd1 protein expression was evaluated in 50 samples, with different types of Gleason grade." (PMID 27105504, 2016). "Few studies have addressed cyclin D1 expression or localisation in primary prostatic adenocarcinomas, and the criteria used to establish positive cyclin D1 staining have been divergent." (PMID 17375037, 2007). "Therefore, the aim of the present study was to perform a pilot evaluation of the expression of miRNAs 106a-5p and 375-3p, as well as β-catenin, Fzd8, Wnt5a, and cyclin D1 in prostate adenocarcinoma compared with BPH." (PMID 41465498, 2025). "To determine whether Slug expression correlates with c-Jun or cyclin D1 expression in human cancers, we analyzed TCGA-generated prostate adenocarcinoma data (MSKCC, Cancer Cell 2010)." (PMID 27385093, 2016). "Based on this rationale, both miRNAs were selected for our study alongside β-catenin, Fzd8, β-catenin and cyclin D1, enabling an integrated assessment of transcript and protein expression patterns in BPH and prostate adenocarcinoma specimens." (PMID 41465498, 2025). "In summary, the results of this study showed significantly higher expression of miR-106a-5p and miR-375-3p in prostate adenocarcinoma tissues compared with BPH, accompanied by lower expression of β-catenin, Fzd8, Wnt5a, and cyclin D1." (PMID 41465498, 2025).
bladder tumor (9 papers, 2001 to 2025). "Aberrant cyclin D1 overexpression has been regarded to be associated with tumorigenesis and is observed in many different cancer types such as lymphoid, breast, esophageal, lung, colorectal, prostate, pancreas and bladder tumors." (PMID 29925351, 2018). "The present study describes the in vivo behavior of CCND1 amplification in chromosome unstable T1 bladder tumors." (PMID 20540739, 2010). "Complex in vivo behavior of CCND1 amplicon in bladder tumor cells has been demonstrated by accurate FISH analysis on paraffin-embedded tumors." (PMID 20540739, 2010). "This is the first study to provide insights into the coexistence of CCND1 amplification in homogeneously staining regions and double minutes in primary bladder tumors." (PMID 20540739, 2010). "Paraffin-sections from 150 newly diagnosed bladder tumours (Ta/T1 = 97; T2-T4 = 53) were stained for cyclin D1 using immunohistochemistry and a cyclin D1 index assigned." (PMID 11161387, 2001). "Among them, 13 genes, including AHR, BCL2L1, CCND1, KRAS, SOX4, MYC, and E2F family genes, were previously reported to have increased expression in BC tissue, and their alterations, either through amplification or upregulation, are linked with bladder tumor initiation or progression." (PMID 40801146, 2025). "Twenty-one paraffin-embedded bladder tumors were analyzed by conventional comparative genome hybridization and fluorescence in situ hybridization (FISH) with a cyclin D1 gene (CCND1)/centromere 11 dual-color probe." (PMID 20540739, 2010). "Bladder tumors were classified according to the CIN index, and we have shown a positive correlation between high heterogeneity, centrosome abnormalities and CCND1 gene amplification." (PMID 20540739, 2010). "Our results demonstrate, for the first time, that CCND1 amplification in DM and HSR could co-exist in the same bladder tumor." (PMID 20540739, 2010). "In the present study, the gene copy number variation analysis of CCND1 in formalin fixed paraffin embedded tissue sections revealed a complex and unprecedented pattern of cellular behavior in non-muscle invasive bladder tumors." (PMID 20540739, 2010).
cholesteatoma (9 papers, 2013 to 2025). A pathologic process characterized by the proliferation of keratinizing squamous epithelium resulting in the accumulation of keratin and cells in the middle ear and/or mastoid. "It is known that NF-κβ acts through a pathway with Ki-67 (the inhibitor of the DNA binding protein 1 (Id1) → NF-κB → cyclin D1 → Ki-67) and activates cell proliferation in human cholesteatoma." (PMID 38535082, 2024). "Another study also revealed that PPARδ/PDK1/PTEN/AKT/GSK3β/Cyclin D1 pathway was involved in the proliferation of keratinocytes in cholesteatoma." (PMID 35151320, 2022). "Previous investigations have demonstrated that the PI3K-Akt-Cyclin D1 signaling cascade is activated in cholesteatoma epithelium and has a critical role in cholesteatoma keratinocytes hyperproliferation." (PMID 34522167, 2021). "Previous researches have proved that the PI3K/Akt/PTEN/Cyclin D1 signaling pathway is indeed active in cholesteatoma epithelium and plays a vital role in cholesteatoma keratinocyte hyperproliferation." (PMID 33424958, 2020). "Taken together, our findings indicate that PPAR β/δ activation promotes cell proliferation in cholesteatoma keratinocytes through the regulation of the PDK1/AKT/PTEN/GSK3β/Cyclin D1 pathway." (PMID 33424958, 2020). "Overall, our data suggested that the proliferating effect of PPAR β/δ on the cholesteatoma keratinocytes was mediated by the positive regulation of the PDK1/PTEN/AKT/GSK3β/Cyclin D1 pathway." (PMID 33424958, 2020). "The immunoblot showed that the GW0742 treatment increased the P-AKT (ser473) and its downstream effector Cyclin D1 and inhibited the level of PTEN, with altering phosphorylation activity of GSK3β in the cholesteatoma keratinocytes." (PMID 33424958, 2020). "In summary, we demonstrated that ligand activation of PPAR β/δ regulates cell proliferation in cholesteatoma keratinocytes and that upregulation of PDK1 and modulation of the AKT/PTEN/GSK3β/Cyclin D1 pathway may be involved." (PMID 33424958, 2020).
dysplasia (9 papers, 2007 to 2025). A usually neoplastic transformation of the cell, associated with altered architectural tissue patterns. "The components of canonical Wnt pathway, such as Wnt3, β-catenin, and cyclin D1, were detected, implying that this pathway is potentially involved in the progression of dysplasia in oral leukoplakia." (PMID 17922924, 2007). "Thus, Wnt/β-catenin pathway is considered to be involved in the progression of dysplasia in oral leukoplakia, as shown by nuclear expression of β-catenin and other components, including Wnt3 and cyclin D1." (PMID 17922924, 2007). "Both the nuclear expression of β-catenin and Wnt3 expression were observed in oral leukoplakia with dysplasia, and therefore the aberrant Wnt signaling pathway may promote malignant transformation by triggering cyclin D1 expression and consequently uncontrolled progression into the cell cycle." (PMID 17922924, 2007). "Cyclin D1 overexpression was more evident in the oral leukoplakia with dysplasia than that without dysplasia, and percentage of the cell number with positive nuclear staining is significantly different in these specimens." (PMID 17922924, 2007).
esophageal adenocarcinoma (9 papers, 2006 to 2023). A malignant tumor with glandular differentiation arising predominantly from Barrett mucosa in the lower third of the esophagus. "In this case-control study of 142 patients with Barrett high-grade dysplasia and esophageal adenocarcinoma, only low cyclin D1 levels were associated with a favorable prognosis for overall survival." (PMID 32058552, 2020). "What is the prognostic significance of human papillomavirus–related biomarkers (ie, retinoblastoma protein, cyclin D1, minichromosome maintenance protein, and Ki-67) in Barrett high-grade dysplasia and esophageal adenocarcinoma?" (PMID 32058552, 2020). "The lymphoproliferation revealed IGH/CCND1 translocation by FISH, but the esophageal adenocarcinoma only showed CCND1 aneuploidy without break-apart signals." (PMID 33425412, 2020).
Hyperglycemia (9 papers, 2013 to 2025). An increased concentration of glucose in the blood. "Although the pRb/E2F complex permits cell progression in the G1 and S phase, in hyperglycemia, hyperphosphorylation of Rb-induced high glucose and cyclin D1 caused cell cycle arrest at G1." (PMID 33007805, 2020). "Further downstream of these events, the increased expression of cell cycle-associated proteins such as CDK2 and Cyclin D1 can accelerate progression through the cell cycle thus leading to an aberrant increase in cell proliferation under hyperglycemia." (PMID 24260287, 2013). "Interestingly, hyperglycemia is able to promote cell cycle arrest via cyclin D1 and p21 upregulation." (PMID 31940810, 2020). "However, in parallel with previous studies, we demonstrate enhanced expression of CDK2 and Cyclin D1 upon exposure to hyperglycemia, indicating an accelerated cell cycle in response to hyperglycemia." (PMID 24260287, 2013). "Moreover, the phosphorylation of Akt, accumulation of β-catenin, and transcription of c-Myc and cyclin D1 were suppressed, in both the artery of hyperglycemia rats and the HG-induced VSMC proliferation model upon ELF consumption or by UroA treatment, respectively." (PMID 29692859, 2018). "In our study, Akt/β-catenin cascade in the arterial tissues of hyperglycemia rats was blocked upon ELF consumption, accompanied by the suppression of c-Myc and cyclin D1 transcription." (PMID 29692859, 2018).
lung squamous cell carcinoma (9 papers, 2016 to 2025). "We found that in lung squamous cell carcinoma, CCND1, the main potential therapeutic target of cinobufotalin injection, was associated with patient survival." (PMID 32148531, 2020). "In the Lung-MAP clinical trial, patients with advanced lung squamous cell carcinoma with CDK4 or CCND1/2/3 amplifications, which are molecularly similar to the p16-null state, were randomized to palbociclib or docetaxel." (PMID 30647837, 2018).
pituitary adenomas (9 papers, 2015 to 2022). "For example, in a Men1 knockout mouse model, loss of cell-cycle control and pituitary tumourigenesis were associated with miR-15a, miR-16-1 and let-7a downregulation and cyclin D1 upregulation in pituitary adenomas compared to normal WT pituitaries." (PMID 35900839, 2022). "This is partially due to Cyclin D1 (CCND1) gene amplification, which occurs in around 25% of pituitary adenomas." (PMID 26793165, 2015). "Importantly, the knockdown of β-Catenin inhibited pituitary adenoma cell proliferation and migration probably by inhibiting AKT, STAT3, Cyclin D1, CDK4, MMP-2, and MMP-9." (PMID 35928898, 2022). "ERα inhibition abolished E2-induced PRLR upregulation and PRL-induced ERα phosphorylation, and fulvestrant, an ERα inhibitor, restored pituitary adenoma cell sensitivity to bromocriptine by activating JNK-MEK/ERK-p38 MAPK signaling and cyclin D1 downregulation." (PMID 33173437, 2020).
pulmonary fibrosis (9 papers, 2006 to 2024). Chronic progressive interstitial lung disorder characterized by the replacement of the lung tissue by connective tissue, leading to progressive dyspnea, respiratory failure, or right heart failure. "Recently, CCND1 has been identified as an ferroptosis hub gene associated with idiopathic pulmonary fibrosis." (PMID 39588389, 2024). "FOXM1 plays a major role in regulating the development of lung fibrosis by inducing the expression of the proliferation-related genes CCNB1, CCND1, and PLK1." (PMID 37238726, 2023). "We observed increased expression of WNT5A, cyclin D1, VEGF, and MMP7, all of which are Wnt target gene products that play an important role in pulmonary fibrosis." (PMID 25331176, 2014). "We also observed increased expression of the Wnt target gene products MMP-7, cyclin D1, VEGF, and AXIN2 that are thought to play an important role in pulmonary fibrosis." (PMID 21935365, 2011).
rhabdoid tumor (9 papers, 2009 to 2024). An aggressive malignant embryonal neoplasm usually occurring during childhood. "Due to the variable staining characteristics of Cyclin D1 in malignant rhabdoid tumors, it cannot be recommended as an immunohistochemical marker in the differential diagnosis." (PMID 35147974, 2022). "A recent finding on targeted therapy revealed that drugs inhibiting cyclin D1 and/or CDKs, such as fenretinide and flavopiridol, are effective in inhibiting rhabdoid tumor growth, correlated with the down-modulation of cyclin D1." (PMID 27733182, 2016). "Gene set enrichment analysis (GSEA) demonstrated that gene programs, which are deregulated by loss of SMARCB1 in rhabdoid tumors (MYC, cyclin D1 and the pluripotency program) are further upregulatedfollowing SAHA treatment." (PMID 23764045, 2013). "A group at Albert Einstein College of Medicine generated Ini1+/− mice and showed that they have an increased incidence of rhabdoid tumors and there is a derepression of cyclin D1." (PMID 22988546, 2012). "While these previous studies have focused on the role of cyclin D1 in rhabdoid tumors, our analyses shed new light on the functional diversity of distinct D-type cyclins and associated CDKs in ATRT to drive cell cycle progression and possibly response to CDK4/6 blockade." (PMID 39617889, 2024). "Rhabdoid tumors and cells are exquisitely dependent on cyclin D1 for genesis and survival, suggesting that targeting the cyclin/cyclin-dependent kinase (cdk) axis may be an effective therapeutic strategy for these tumors." (PMID 19750188, 2009). "Currently, there are several studies regarding the use of a pan-cdk inhibitor, flavopiridol, that both inhibits cdk activity and transcriptionally down-modulates cyclin D1 which may effectively inhibit rhabdoid tumor growth." (PMID 19750188, 2009). "Transcriptional profiling showed that CCND1 and EZH2 overexpression may play an important role in rhabdoid tumors." (PMID 31462227, 2019). "Repression of cyclin D1 expression, by INI1, is a key pathway in the genesis of rhabdoid cancers." (PMID 23861745, 2013). "They then crossed Ini1+/− mice with cyclin D1−/− mice and found that without cyclin D1 expression, rhabdoid tumors failed to develop." (PMID 22988546, 2012).